CRY2 (cryptochrome circadian regulator 2)
Diseases named in the same sentence as CRY2 in open-access papers (continued):
Sharing a sentence is not in itself a finding about the gene and the disease.
osteosarcoma (5 papers, 2021 to 2024). A usually aggressive malignant bone-forming mesenchymal neoplasm, predominantly affecting adolescents and young adults. "In this connection, in the human osteosarcoma U2OS cell line, BMAL1 KD diminished metabolite rhythms, while CRY1 or CRY2 perturbation generally shortened/lengthened rhythms, respectively." (PMID 36183836, 2022). "Herein, the same core circadian clock genes that are rhythmically controlled by CRY1 in osteosarcoma cells are also bound by CRY1 in PCa (i.e., CRY1, CRY2, PER2, and PER3) showing concordance of binding across models regardless of circadian synchronization." (PMID 33452241, 2021).
ovarian carcinoma (5 papers, 2015 to 2024). A malignant neoplasm originating from the surface ovarian epithelium. "The expression level of CRY2 in ovarian cancer is remarkably lower than those in normal ovary." (PMID 29513728, 2018). "The goal of the current study was to examine single nucleotide polymorphisms (SNPs) in circadian genes BMAL1, CRY2, CSNK1E, NPAS2, PER3, REV1 and TIMELESS and downstream transcription factors KLF10 and SENP3 as predictors of risk of epithelial ovarian cancer (EOC) and histopathologic subtypes." (PMID 26807442, 2015). "We further evaluated the correlations between PER1 and these 10 interacting proteins based on the GEPIA database and found that the expression of PER1 in ovarian cancer was correlated with that of ARNTL, CLOCK, CRY1, CRY2, CSNK1D, CSNK1E, NPAS2, and PER3." (PMID 34220965, 2021).
sleep disorder (5 papers, 2021 to 2025). A change from the patient's baseline sleeping pattern, in the hours slept and/or an alteration/dysfunction in the stages of sleep. "Additionally, CRY2 plays a crucial role in sleep disorders, including its association with familial advanced sleep phase (FASP)." (PMID 40487778, 2025). "Circadian rhythm genes mainly altered in malignant nodules, and sleep disorders may be involved in the occurrence of elderly thyroid malignancy through the high expressions of CLOCK and BMAL1, and low expression of CRY2." (PMID 34211057, 2021).
Arthritis (4 papers, 2012 to 2024). Inflammation of a joint. "Global deletion of Nfil3, Cry1 and/or Cry2 worsens disease severity in experimental arthritis models." (PMID 38981514, 2024). "Once treated with anti-TNF-α antibodies, Cry1−/−Cry2−/− mice progression of arthritis was halted, suggesting that the circadian rhythm and arthritis affect each other, and disruptions in the circadian rhythm mouse clock genes Cry1 and Cry2 may hasten the progression of inflammatory arthritis." (PMID 37378201, 2023). "Mice lacking CRY1 and CRY2 have increased levels of activated T cells, and when arthritis was induced in these mice, serum IL6 levels were higher than in wild type mice with induced arthritis." (PMID 35886000, 2022).
colon cancer (4 papers, 2013 to 2022). "Altered CRY1 and CRY2 expression patterns and the interplay with the genetic landscape in colon cancer cells may underlie phenotypic divergence that could influence disease behavior as well as CRC patients survival and response to chemotherapy." (PMID 26768731, 2016). "One study found that Cry1 and other circadian gene (Cry2, Per2 and BamlI) mRNA expression levels were similar in colon cancer and adjacent normal mucosa." (PMID 23626715, 2013). "Overall, the phenotypic differences among the colon cancer cell lines investigated may underlie diverse CRY1 and CRY2 expression patterns and a related genetic landscape that could influence cell survival and response to chemotherapy." (PMID 26768731, 2016). "The different CRY1 and CRY2 expression levels and time related profiles plus the different apoptotic, proliferative and cytotoxic responses observed in vitro in the studied colon cancer cell lines could be related to the dissimilarity in their chromosomal abnormalities and genetic background." (PMID 26768731, 2016).
chronic myeloid leukemia (3 papers, 2010 to 2017). "The expression of Per1, Per2, Per3, Cry1, Cry2, and Bmal1 is significantly impaired in both chronic phase and blast crisis of chronic myeloid leukemia (CML) samples compared with those in normal samples." (PMID 20353609, 2010). "Disrupted CRY2 and PER2 are associated with non-Hodgkin’s lymphoma and the initiation and/or progression of AML, respectively, and CpG islands of PER3 are highly methylated in all patients with chronic myelogenous leukemia." (PMID 28487473, 2017). "In addition, all of the core clock genes were down-regulated in both chronic forms of leukemia (chronic myeloid leukemia and chronic lymphocytic leukemia), except for Cry2, which was not affected when the disease was diagnosed." (PMID 30210557, 2017).
dysthymia (3 papers, 2013 to 2017). "Four CRY2 genetic variants (rs10838524, rs7121611, rs7945565, rs1401419) associated significantly with dysthymia (false discovery rate q<0.05)." (PMID 23951166, 2013). "Although preliminary, our analysis has demonstrated that CRY2 associates robustly with dysthymia which is characterized by a chronic course of illness where a depressive episode lasts for two years or longer and often deepens into a major depressive episode." (PMID 23951166, 2013). "Of the individual CRY2 SNPs, rs7121611 (upstream), rs10838524 (intron 1), rs7945565 (intron 2) and rs1401419 (intron 2) showed evidence of association with dysthymia, with the A, G, G and G alleles being predisposing, respectively." (PMID 23951166, 2013). "Our main finding was that CRY2 genetic variants associated with dysthymia in our random sample derived from the general population aged 30 years and older." (PMID 23951166, 2013). "Four CRY2 SNPs showed evidence of association with dysthymia using the additive model (rs10838524 risk allele G, p = 0.000020, OR = 1.75; rs7121611 risk allele A, p = 0.000022, OR = 1.74; rs7945565 risk allele G, p = 0.000039, OR = 1.71; rs1401419 risk allele G, p = 0.000041, OR = 1.71)." (PMID 23951166, 2013). "To conclude, CRY2 genetic variants associated with dysthymia." (PMID 23951166, 2013). "Here we report a significant association of CRY2 genetic variants with dysthymia." (PMID 23951166, 2013). "This difference could explain why CRY2, not CRY1, associated with dysthymia in our study." (PMID 23951166, 2013).
hepatocellular carcinoma (3 papers, 2020 to 2022). A malignant tumor that arises from hepatocytes. "Interestingly, ANKRD47 promotes cell invasion in hepatocellular carcinoma in an oxygen-dependent manner, while the circadian clock gene CRY2 correlates with overall survival in breast, pancreas, colon and liver cancer." (PMID 33527138, 2021). "For example, Cry1 and Cry2 overexpression was associated with poor OS in gastric cancer and CRC; Npas2 was frequently upregulated in hepatocellular carcinoma (HCC) and its overexpression significantly contributed to poor prognosis of HCC patients." (PMID 32437452, 2020).
Hypertension (3 papers, 2011 to 2020). The presence of chronic increased pressure in the systemic arterial system. "In contrast, gene expression profiling of Spontaneously Hypertensive (SHR) rats, a genetic model of hypertension, demonstrated decreased expression of Bmal1 and Npas2, while Per1, Per2, Per3, Cry1, Cry2, Bhlhe41 and Csnk1D were all upregulated compared to naïve WKY controls." (PMID 33127986, 2020).
lymphoma (3 papers, 2016 to 2024). A malignant (clonal) proliferation of B- lymphocytes or T- lymphocytes which involves the lymph nodes, bone marrow and/or extranodal sites. "Previous studies demonstrated that mutation or knock out of clock genes Per2, Cry1/Cry2 or Bmal1 also accelerated the development of lymphomas following whole body exposure to γ radiations." (PMID 27494874, 2016). "Conversely, research has demonstrated that the removal of CRY2 results in an exacerbation of MYC-mediated lymphoma development in murine models." (PMID 39012661, 2024). "We therefore expected that CJL could influence MYC-driven lymphoma by disrupting CRY2-mediated turnover of c-MYC." (PMID 37811199, 2023). "Cry2 can promote ubiquitination and degradation of c-MYC, whereas deletion of Cry2 leads to enhancement of MYC-driven lymphoma in mice." (PMID 39012661, 2024).
non-Hodgkin lymphoma (3 papers, 2017 to 2023). Distinct from Hodgkin lymphoma both morphologically and biologically, non-Hodgkin lymphoma (NHL) is characterized by the absence of Reed-Sternberg cells, can occur at any age, and usually presents as a localized or generalized lymphadenopathy associated with fever and weight loss. "Three CRY2 SNPs, rs11038689, rs7123390 and rs1401417, were found to be associated with risk of developing non-Hodgkin lymphoma (NHL) in a predominantly Caucasian cohort consisting only of female patients." (PMID 37761843, 2023).
pancreatic cancer (3 papers, 2019 to 2025). "Towards this direction, we have focused herein on the pivotal clock component CRY2, which is critically implicated in DNA repair, cell cycle regulation, and chemoresistance modulation, thereby rendering CRY2 a novel and important (druggable) target for pancreatic cancer therapy." (PMID 39796036, 2024). "Taken together, our results strongly suggest that TH301 exerts opposite actions on p21 (remarkable induction) and Survivin (notable reduction) protein expression patterns that occur independently of CRY2 modulation in human pancreatic cancer cell settings." (PMID 39796036, 2024). "Most importantly, the p21 induction observed herein, in response to TH301 treatment, seems to occur independently of both CRY2 and BMAL1 modulation, thus indicating the involvement of alternative pathways, successfully operating in pancreatic cancer cell environments of diverse mutational loads." (PMID 39796036, 2024). "It has been demonstrated that clock genes, including PER1 and CRY2, are down-regulated, whereas ID2 is over-expressed in pancreatic cancers." (PMID 30934731, 2019).
thyroid cancer (3 papers, 2021 to 2023). "They found up-regulation of BMAL1 and the downregulation of CRY2 in tissues sampled from well-differentiated thyroid cancer." (PMID 36293065, 2022). "We found that the mRNA expression of CLOCK and BMAL1 in thyroid carcinoma tissues (PTC) was significantly higher than that in benign and normal tissues, while the expression of CRY2 was decreased, indicating that circadian biological rhythm was involved in the occurrence of the disease." (PMID 34211057, 2021).
acute myeloid leukemia (2 papers, 2017 to 2021). Acute myeloid leukemia (AML) is a group of neoplasms arising from precursor cells committed to the myeloid cell-line differentiation. "Expression profiling for both core and ancillary clock genes revealed that the majority of clock genes are down-regulated in acute myeloid leukemia patients, except for Cry2, which is up-regulated towards the end of treatment." (PMID 30210557, 2017).
alcohol use disorder (2 papers, 2022). "Clinical investigations report reduced baseline Clock mRNA levels in patients with alcohol use disorder, as well reduced baseline mRNA levels of circadian proteins BMAL1, Per1, Per2, Cry1, and Cry2." (PMID 35456507, 2022).
Alzheimer disease (2 papers, 2020 to 2024). A progressive, neurodegenerative disease characterized by loss of function and death of nerve cells in several areas of the brain leading to loss of cognitive function such as memory and language. "Given the vital role of CRY2 in the brain, we hypothesize that CRY2 plays a critical role in sleep deprivation to exacerbate cognitive dysfunction in Alzheimer’s disease (AD)." (PMID 39012854, 2024).
brain tumor (2 papers, 2024 to 2025). "Genes including CRY2, NR1D2, and PER3, were found to have a positive correlation with high overall survival (OS) and disease-free survival (DFS) in brain tumor patients." (PMID 39043735, 2024).
Cluster headache (2 papers, 2021 to 2025). A type of headache characterized by repeated attacks of unilateral pain lasting 15 to 180 minutes and associated with local autonomic signs. "Lithium,indicated as a prophylactic treatment for cluster headache has been found to significantly increase the expression of Per2 and Cry1, and reduce the expression of Per3, Cry2, and Bmal1." (PMID 39560176, 2025). "One Swedish case-control study investigated the role of four SNPs within CRY1 and CRY2 genes in cluster headache; they selected rs2287161, rs8192440, rs10838524, and rs1554338 SNPs according to previous associations between them and several neurological and psychiatric disorders." (PMID 39560176, 2025). "In this case-control study, we investigated the role of cryptochrome (CRY) genes in cluster headache by screening 628 cluster headache patients and 681 controls from Sweden for four known genetic variants in the CRY1 (rs2287161 and rs8192440) and CRY2 (rs10838524 and rs1554338) genes." (PMID 34256648, 2021).
esophageal cancer (2 papers, 2016 to 2024). A primary or metastatic malignant neoplasm involving the esophagus. "UCHL3 promotes the malignant progression of esophageal carcinoma by influencing CRY2 methylation." (PMID 38965582, 2024). "The esophageal cancer cells were negatively isolated by MACS and subjected to RT-qPCR to detect the expression of circadian clock molecule mRNA, including NFIL3, Per1, Per2, Bmal1, Cry1, Cry2, Clock and Npas2." (PMID 26898709, 2016).
Glucose intolerance (2 papers, 2017 to 2020). Glucose intolerance (GI) can be defined as dysglycemia that comprises both prediabetes and diabetes. "Genetic loss of CRY1/CRY2 results in decreased glucose intolerance, increased glucose level, and constitutively high levels of circulating corticosterone in mice." (PMID 28352282, 2017). "In mice, the loss of Cry1 and/or Cry2 resulted in glucose intolerance and constitutively high levels of circulating corticosterone, suggesting reduced suppression of the hypothalamic-pituitary-adrenal (HPA) axis coupled with increased glucocorticoid transactivation in the liver." (PMID 32437460, 2020).
head and neck squamous cell carcinoma (2 papers, 2019 to 2022). A squamous cell carcinoma that arises from any of the following anatomic sites: lip and oral cavity, nasal cavity, paranasal sinuses, pharynx, larynx, and salivary glands. "In comparison to the pericarcinomatous tissue of head and neck squamous cell carcinoma (HNSCC) patients, clock genes Bmal1, Pers, and Crys, especially Cry2, showed a downward trend in cancer tissue." (PMID 36467684, 2022).
Impaired glucose tolerance (2 papers, 2020 to 2022). An abnormal resistance to glucose, i.e., a reduction in the ability to maintain glucose levels in the blood stream within normal limits following oral or intravenous administration of glucose. "Both Cry2 and Per2 SNPs have been associated with impaired glucose tolerance, while Per2 SNPs have also been associated with binge eating and stress related to dieting, leading to increased weight gain." (PMID 36034454, 2022). "Murine cry1 and cry2 gene deletions are associated with disruptions in the circadian rhythmicity of insulin and glucagon secretion, which in turn are associated with insulin resistance, hypertension and impaired glucose tolerance and dyslipidemia." (PMID 36034454, 2022). "Studies have found that mice carrying null mutations in cryptochrome circadian regulator 2 (Cry2) gene have a number of metabolic abnormalities, including increased insulin sensitivity, impaired glucose tolerance, reduced adipose tissue and body weight, and abnormal circadian rhythmicity." (PMID 32653024, 2020).
melanoma (2 papers, 2012 to 2023). A malignant, usually aggressive tumor composed of atypical, neoplastic melanocytes. "CRY2, the most important gene controlling cell circadian rhythm, shows down-regulation only in VGP melanoma among all the cancer types under consideration." (PMID 22295108, 2012).
myocardial infarction (2 papers, 2020 to 2021). Gross necrosis of the myocardium, as a result of interruption of the blood supply to the area, as in coronary thrombosis. "The genetic variability in the ARNTL, CLOCK, CRY2 and PER2 genes in this study showed that variations in the circadian genes differ between women and men with myocardial infarction." (PMID 34066863, 2021). "This study aimed to examine the potential difference of single nucleotide polymorphisms (SNPs) of the circadian rhythm genes ARNTL, CLOCK, CRY2 and PER2 in women and men with myocardial infarction." (PMID 34066863, 2021). "Furthermore, probably, analyzed polymorphisms in the ARNTL, CRY2, and PER2 genes are not functionally associated with myocardial infarction." (PMID 34066863, 2021).
non-small cell lung carcinoma (2 papers, 2023). A group of at least three distinct histological types of lung cancer, including non-small cell squamous cell carcinoma, adenocarcinoma, and large cell carcinoma. "LINC01234 interacts with HNRNPA2B1, leading to the recruitment of DGCR8 and promoting the processing and maturation of miR-106b-5p, which inhibits CRY2 and promotes the growth of non-small cell lung cancer (NSCLC) cells." (PMID 37151887, 2023).
Pancreatic Ductal Adeno-Carcinoma (2 papers, 2022 to 2024). "Altogether, this study demonstrates the potential and promise of TH301, a novel CRY2 molecular stabilizer, to act as a new therapeutic agent for Pancreatic Ductal Adeno-Carcinoma (PDAC)." (PMID 39796036, 2024).
septic shock (2 papers, 2021 to 2025). Shock caused by infection; frequently caused by gram negative bacteria, although some cases have been caused by other bacteria, viruses, fungi, and protozoa; characterized by fever, chills, tachycardia, tachypnea, and hypotension. "In a study of circadian rhythms in septic shock, CRY2 and NR1D2 had the highest rhythmicity in patients." (PMID 40362233, 2025). "In summary, the positive regulators of the transcriptional–translation feedback loop (CLOCK and ARNTL) were the least rhythmic, while negative regulators (NR1D1, NR1D2, CRY2) were the most rhythmic in septic shock patients." (PMID 33900485, 2021). "While CRY1, NR1D1, NR1D2, DBP, PER2 were suppressed in septic shock patients, CRY2, surprisingly was significantly upregulated compared to healthy young men." (PMID 33900485, 2021). "In addition, the expression of the clock genes CRY1, NR1D1, NR1D2, DBP, and PER2 were suppressed in septic shock patients, whereas CRY2 was significantly upregulated compared to healthy young men." (PMID 33900485, 2021).
Abdominal obesity (1 paper, 2021). Excessive fat around the stomach and abdomen. "In the AAs the most common SNPs in circadian clock genes were in Cry2 (rs2292912) and Clock (rs6850524), with consistently higher MAFs when compared to that reported in European and Asian populations, which have been associated with susceptibility to abdominal obesity and T2D." (PMID 34141862, 2021).
acne (1 paper, 2022). An inflammatory process of the sebaceous glands which is characterized by comedones, nodules, papules and/or pustules on the skin. "We found that Bmal1 and its target genes Rev-erbα, Dbp, Per1 and Cry2 were down-regulated in the skin of P. acnes-treated mice, suggesting a role of Bmal1 in the condition of acne." (PMID 35414779, 2022).
acute lymphocytic leukemia (1 paper, 2017). "A similar process was seen in acute lymphocytic leukemia patients; however, here, Cry2 expression came back up towards control levels upon treatment completion." (PMID 30210557, 2017).